APOE (apolipoprotein E)
Diseases named in the same sentence as APOE in open-access papers (continued):
Sharing a sentence is not in itself a finding about the gene and the disease.
atherosclerosis (continued). "The number of B-1 cells secreting anti-atherosclerotic IgM is reportedly reduced in PVAT from apolipoprotein E-/- (ApoE-/-) mice, which significantly aggravates atherosclerosis in the aorta and coronary artery." (PMID 34456867, 2021). "In this study, we used the ApoE−/− mouse model of atherosclerosis to study the cardiovascular effects of binge drinking." (PMID 33796575, 2021). "These outcomes indicated that reduced miR-146a-5p expression aggravated atherosclerosis in apoE−/− mice and also facilitated the accumulation of lipids in ox-LDL-treated THP-1 cells." (PMID 34820432, 2021). "A thin fibrous cap in the lesion, which is indicative of unstable plaques prone to rupture and increased atherosclerosis correlate with increased Th17 cells, IL-23-producing vascular muscle, and macrophages in apoE/IL18 double-KO mice." (PMID 35087531, 2021). "Firstly, salidroside ameliorated CIH-induced atherosclerosis progression and barrier injury in normal chow diet-fed ApoE-/- mice." (PMID 34504429, 2021). "The development of TMAO-induced atherosclerosis was considerably blocked by L. plantarum ZDY04 in ApoE-/- mice treated with 1.3% choline as compared with the control group." (PMID 34445037, 2021). "Luo and colleagues found that AKT/eNOS signaling pathways are involved in endothelial protection against high-fat diet-induced atherosclerosis in ApoE−/− mice." (PMID 33841146, 2021). "In fact, propagermanium, a drug used clinically for the treatment of chronic hepatitis in Japan, inhibits C-C chemokine receptor 2 function and reduces macrophage infiltration and atherosclerosis in Apolipoprotein E (ApoE) knockout mice." (PMID 33803115, 2021). "Apolipoprotein E-knockout (apoE−/−) mice that spontaneously develop atherosclerotic lesions, hypercholesterolemia, and dyslipidemia are a popular animal model of atherosclerosis." (PMID 34070749, 2021). "The results of Phinikaridou and colleagues who investigated vessel wall signal enhancement in ApoE-/--mice with advanced atherosclerosis and pravastatin treatment are in agreement with our results." (PMID 34681063, 2021). "Deletion of NOX4 in ApoE−/− mice fed a high fat diet accelerated atherosclerosis development and resulted in greater disease development after partial carotid artery ligation." (PMID 34571964, 2021). "We confirmed that nicotine triggered NLRP3 inflammasome activation and induced macrophage migration into atherosclerotic plaque, thus accelerated atherosclerosis in apoE–/– mice fed with a high-fat diet." (PMID 34490270, 2021). "Recent animal studies have shown that CTRP9 attenuates atherosclerosis through the inflammasome and autophagy signaling pathway in ApoE KO mice." (PMID 34744738, 2021). "To compare the expression levels of CCR6 in B-1 and B-2 cells, we performed flow cytometry on isolated cells from various compartments and measured the frequency of CCR6+ B-1 and B-2 cells from atherosclerosis prone chow fed ApoE−/− mice." (PMID 33679793, 2021). "In an ApoE−/− mouse model where CXCR6 was replaced with a green fluorescent protein CXCR6GFP/GFP, a decrease in atherosclerosis was observed when compared with ApoE−/− mice." (PMID 33503867, 2021). "The observation that both the ApoE-/- Aid-/- and ApoE-/- mice have elevated IgM titers, suggests a more complex dynamic where IgM titers by themselves are insufficient at controlling atherosclerosis." (PMID 34305930, 2021). "DGLA also attenuates atherosclerosis in ApoE−/− mice although the role of STAT1 S727 phosphorylation has not been investigated." (PMID 34569651, 2021). "Second, the effects of swiprosin-1 deficiency in bone marrow-derived monocytes/macrophages in the development and progression of atherosclerosis were investigated in ApoE−/− mice fed with a high-cholesterol diet (HCD)." (PMID 34759279, 2021).
atherosclerosis (continued). "In the context of the ApoE knockout on a Western diet, knockdown of GPx1 accelerated atherosclerosis in mice as well as in mice with streptozotocin-induced diabetes, indicating that in susceptible models GPx1 regulates atherogenesis." (PMID 34579115, 2021). "In atherosclerosis-prone ApoE-/-CD11c-YFP+ mice, APC and CD4+ T helper cell interactions were increased in the plaque that resulted in pro-inflammatory cytokine IFN-γ and TNF-α secretion." (PMID 34987524, 2021). "Here, we explored the feasibility of tracking atherosclerosis by targeting Gal3 expression in plaques of apolipoprotein E knockout (ApoE-KO) mice via PET imaging." (PMID 33408786, 2021). "To determine the role of Sub1 in TLR signaling‐induced atherosclerosis, we applied myeloid‐specific Sub1 KO in the chow‐fed ApoE−/− murine model of atherosclerosis." (PMID 34378353, 2021). "The impact of acacetin injection on the development of atherosclerosis in apoE‐/‐ mice was assessed." (PMID 33241629, 2021). "The role of platelet sCD62P atherogenesis has also been evidenced in the ApoE-deficient mouse model, because mice receiving CD62P-deficient platelets developed less atherosclerosis than mice receiving CD62P expression." (PMID 34360659, 2021). "To determine the role of H. pylori-derived OMVs in the pathogenesis of atherosclerosis, we intragastrically administered OMVs from H. pylori into ApoE–/– mice for 4 weeks." (PMID 34790655, 2021). "In a study on mouse models with apolipoprotein E deficiency (Apoe −/−), intraperitoneal injection of SAP inhibits atherosclerosis in these animals." (PMID 34948066, 2021). "GP-17 treatment (50 mg/kg) significantly decreased blood lipid levels, increased the expression of antioxidant enzymes, and decreased atherosclerotic lesion size, thus effectively preventing the progression of atherosclerosis in ApoE-/- mice." (PMID 34684830, 2021). "What is more, MβCD inhibited nicotine-triggered NLRP3 inflammasome activation and reduced nicotine-induced macrophage recruitment to atherosclerotic plaque, thus preventing the progression of atherosclerosis in the aorta of apoE–/– mice fed with high-fat diet." (PMID 34490270, 2021). "Coincidentally, trimethylamine N-oxide (TMAO), an intestinal metabolite, treatment also confirmed the consistency between ECs pyroptosis and atherosclerosis in ApoE−/− mice." (PMID 34122076, 2021). "On the other hand, miR-25-3p attenuates oxidized low-density lipoprotein-mediated coronary vascular endothelial cell inflammation by targeting Adam10 in ApoE–/– mouse models of atherosclerosis." (PMID 35069547, 2021). "Metformin (300 mg/kg/d) is observed to suppress the progression of atherosclerosis through the inhibition of DRP1-mediated mitochondrial fission in STZ-induced diabetic ApoE-/- mice." (PMID 34646376, 2021). "The objective of this study is to delineate the mechanism by which different apoE isoforms expressed in myeloid cells influence inflammation and the consequential effect on atherosclerosis." (PMID 34425108, 2021). "To investigate the pathogenesis of atherosclerosis, we evaluated AS plaque-lesion formation in the experimental AS model ApoE−/− mice by oil red O staining." (PMID 33839698, 2021). "In fact, it has been also demonstrated that luteolin can suppress also oxLDL-induced inflammation via the inhibition of STAT3 activation, and that it is able to counteract the development and progression of atherosclerosis in ApoE−/− mice with HFD." (PMID 33525692, 2021). "It is widely acknowledged that ApoE mice fed a high-fat diet can be used to establish an advanced atherosclerosis model." (PMID 33436015, 2021).
atherosclerosis (continued). "Herein, the ApoE−/− mice model of atherosclerosis was used, and blood vessels with an atherosclerotic plaque were studied." (PMID 34539804, 2021). "PVAT transplantation from these animals into ApoE−/− recipient mice fed a normal chow diet induced an increase in atherosclerosis development." (PMID 33643076, 2021). "This study aims to investigate the mechanism of NAR in high-fat-diet (HFD)-induced atherosclerosis (AS) in apolipoprotein E-knockout (ApoE-/-) mice." (PMID 33624733, 2021). "Functional depletion of Tregs with anti-CD25 antibody results in an increase of atherosclerosis in ApoE–/– mice, suggesting that Tregs suppress atherogenesis in ApoE–/– mice." (PMID 34622804, 2021). "It is well-known that regular exercise has preventive effects on various organs of atherosclerosis-prone ApoE KO mice." (PMID 34206159, 2021). "Another transcription factor Nrf2 promotes atherosclerosis by raising LDL levels in ApoE knockout mice." (PMID 34439528, 2021). "Lentivirus-mediated NFIA overexpression increased HDL-C circulation, decreased LDL-C cholesterol, and very-low-density lipoprotein cholesterol (VLDL-C) circulation, which resulted in the regression of atherosclerosis in apoE−/− mice." (PMID 34179148, 2021). "MMP-9 is involved in all stages of atherosclerosis and MMP-9 deletion is associated with reduced plaque size, macrophage content and collagen deposition in aortic lesions of ApoE-/- mice." (PMID 34797846, 2021). "In this study, we examined the role of Grp94 in oxLDL-induced autophagy, cell injury in VECs, and atherosclerosis in apolipoprotein E−/− (apoE−/−) mice." (PMID 34938782, 2021). "ApoE−/− mice can spontaneously develop atherosclerosis; thus, they are commonly used as the animal model for atherosclerosis research." (PMID 33977048, 2021). "The protective effect of PEA-15−/− was therefore maintained in the PEA-15−/−/ApoE−/− mouse model and translated into protection in atherosclerosis." (PMID 33772049, 2021). "To investigate the role of HuR in atherosclerosis, we fed ApoE−/− mice with an ND or HFD for 12 weeks." (PMID 33837179, 2021). "Protective effects of irisin on atherosclerosis were reported in two different ApoE KO mouse models." (PMID 34206159, 2021). "Genetic ablation of apolipoprotein E (ApoE) in rodents and rabbits has been used as a promising animal model of lipid metabolism and atherosclerosis." (PMID 34366712, 2021). "ApoE−/− mice are also an established model of atherosclerosis, with a history of atherosclerosis predictive of PI, while a primary diagnosis of atherosclerosis is associated with a greater likelihood of developing a hospital acquired PI18." (PMID 33674592, 2021). "Other risk factors for sporadic AD, which constitute more than 95% of AD cases, are the presence of the ε4 allele for apolipoprotein E (APOE), hypertension, atherosclerosis, hypercholesterolemia, traumatic brain injury, among others." (PMID 33967682, 2021). "Moreover, in constitutively high cholesterol levels apolipoportein E (apoE)-deficient/globular adiponectin transgenic mice globular adiponectin could inhibit development of severe atherosclerosis in the aorta as compared to apoE-deficient control transgenic animals." (PMID 35018766, 2021).
atherosclerosis (continued). "In the present study, we aimed to determine the effects of diet and Cyp17a1 genotype on the composition of the microbiota in a mouse model of atherosclerosis (ApoE KO)." (PMID 34070975, 2021). "To assess the effect of lipid raft on nicotine-accelerated atherosclerosis, we fed apoE–/– mice a high-fat diet containing nicotine for 12 weeks, and MβCD was administrated in the last 4 weeks." (PMID 34490270, 2021). "Expression of the ApoE4 allelic variant of ApoE had previously been shown to increase plasma low-density lipoprotein (LDL) levels and increase the risk for atherosclerosis." (PMID 34248607, 2021). "Several studies have shown that dietary polyphenols, especially theaflavin and quercetin, ameliorate atherosclerosis by improving inflammation and bioavailability of NO in apoE−/− mice." (PMID 34834858, 2021). "It has been proved that α1-nAchR played an important role in nicotine-mediated atherosclerosis, evidenced by the silence of α1-nAchR that resulted in restrained atherosclerotic plaque area in apoE–/– mice." (PMID 34490270, 2021). "Inhibition of PDGF signaling significantly reduces the development of atherosclerotic lesions in APOE null mice, a well-established model of accelerated atherosclerosis." (PMID 33761122, 2021). "It is important to note that this study was used genetically normal animals instead of apolipoprotein E knock-out mice, because evaluating this topic in normal animals is far closer to natural process of atherosclerosis." (PMID 34580342, 2021). "Recently, this phenomenon was reported in brain arteries of obese rats, and was suggested as a contributory factor in endothelial dysfunction during atherosclerosis in apolipoprotein E knockout (apoE-/-) mice." (PMID 34206365, 2021). "Pre-clinical studies have shown that cyclodextrin can promote atherosclerosis regression in ApoE–/– mice by reprogramming macrophages (i.e., increased oxysterol production and consequent LXR-mediated increase of cholesterol efflux)." (PMID 33855029, 2021). "These were reflected in in vivo studies, which showed that there was less atherosclerosis plaque formation in ApoE–/– mice treated with LPS-depleted OMVs or CagA-negative OMVs." (PMID 34790655, 2021). "Male mice were used in this study because previous research has shown that deficiency of the cytokine IFN‐γ, which activates ERK1/2 and STAT1, demonstrates gender specific effects on atherosclerosis in ApoE−/− mice." (PMID 34569651, 2021). "EpK peptide, however, reduced atherosclerosis in apoE-null mice after lentivirus-mediated hepatic expression." (PMID 33800446, 2021). "Another ROS-redox-sensitive factor TXNIP is found to be associated with enhanced oxidative stress and inflammation leading to atherosclerosis in ApoE KO mouse model of diabetes." (PMID 34829831, 2021). "Correspondingly, studies showed that melatonin and PPB alleviate atherosclerosis in HFD-fed ApoE−/− mice via inhibiting NF-κB-mediated pyroptosis in ECs." (PMID 34122076, 2021). "Atherosclerosis was induced in APOE -/- mice in physiological fashion by 8-week Western diet, and vaccination and PTV treatment were conducted prior to P. gingivalis." (PMID 33976982, 2021). "For instance, myeloid Bmal1 deletion in mice has been purported to worsen atherosclerosis driven by ApoE knockout by enhancing vascular inflammation." (PMID 34858390, 2021). "In apolipoprotein E (ApoE) deficient mice with hemizygous KLF2 deficiency, there is a notable increase in atherosclerosis." (PMID 34512715, 2021). "In ApoE-deficient mice, the expression of DKK3 was involved in the pathogenesis of atherosclerosis via the Wnt/β-catenin pathway." (PMID 34631806, 2021). "It was shown that ApoE−/− mice fed a high methionine diet had a greater incidence of arterial plaques characteristic of atherosclerosis." (PMID 34638614, 2021).
atherosclerosis (continued). "Apolipoprotein E (ApoE), an important mediator of lipid transportation in plasma and the nervous system, plays a large role in diseases such as atherosclerosis and Alzheimer's." (PMID 33996741, 2021). "Next, LDC000067 was applied to the ApoE-/- mice to explore the potential role of CDK9 in atherosclerosis." (PMID 34102609, 2021). "Based on the results of the in vitro cell experiments, a high-fat diet (HFD)-induced model of atherosclerosis development was used in ApoE KO mice." (PMID 34884889, 2021). "Specifically, ApoE–/– mice were placed on a high-fat diet at 8 weeks of age for 18 weeks to induce atherosclerosis." (PMID 34338228, 2021). "Losartan, captopril, and DIZE were found to have beneficial effects on various aspects of atherosclerosis development in ApoE-KO mice and other animal models due to their ability to regulate ACE2." (PMID 34206708, 2021). "Further studies employing ApoE−/− mice deficient in PINK1 would allow investigation of the direct role of mitophagy in the development of vascular calcification and atherosclerosis." (PMID 33816463, 2021). "ApoE-/- mice fed with high-fat diet exhibit accelerated atherosclerosis plaques formation and dysfunctional lipid metabolism characterized by the elevated level of triglyceride (TG), total cholesterol (TC) and LDL-C." (PMID 33901014, 2021). "An animal study showed that proinflammatory microbiota from Caspase-/- mice transplanted into atherosclerosis-prone ApoE-/- mice intensifies systemic inflammation and augments atherosclerosis." (PMID 33805303, 2021). "In an atherosclerosis model induced by a high-fat diet, Il12a deletion ameliorated atherosclerotic lesion formation and macrophage infiltration in apolipoprotein E (ApoE) KO mice." (PMID 34276358, 2021). "High levels of serum IL-12 were detected in animal experiments using atherosclerosis-induced ApoE knockout mice." (PMID 34071276, 2021). "Oil red O staining of aortic root sections and whole aorta also demonstrated reduced atherosclerotic lesions area in HMD‐fed ApoE−/− mice injected with Lv‐miR‐195‐3p, indicating miR‐195‐3p overexpression protects mice from the development of atherosclerosis." (PMID 34592792, 2021). "The HFD-induced atherosclerosis model was established based on ApoE(-/-) mice fed the HFD diet for 12 weeks having a larger atherosclerotic plaque area than that of ApoE(-/-) mice fed a normal diet (P=0.004)." (PMID 33626512, 2021). "It has been demonstrated that PG can reduce atherosclerosis in apolipoprotein E knockout mice via inhibition of macrophage infiltration." (PMID 34345249, 2021). "As potential animal models for studies of atherosclerosis, the hApoE KI and ApoE KO rats were fed with an atherogenic PD." (PMID 34361033, 2021). "When null in apolipoprotein E (Apoe−/−), mice develop spontaneous hyperlipidemia and atherosclerosis in the carotid arteries and other large and medium‐sized arteries." (PMID 34110700, 2021). "These in vivo data suggested that sterol-resistant SCAP overexpression in VSMCs promoted the development of atherosclerosis and contributed to plaque stability in ApoE-/- mice." (PMID 34094640, 2021). "ApoE-/- mice developed severe atherosclerosis and inflammation in the aorta compared to the WT groups, and aged apoE-/- mice suffered from a more severe AS lesion than their younger counterparts and had low-grade systemic inflammation." (PMID 33816331, 2021). "Two independently generated 11β-HSD1 knockout strains crossed with ApoE−/− mice demonstrated similar protection from atherosclerosis." (PMID 34299240, 2021). "Separately, the ability of fingolimod to boost Tregs in spleen and blood of ApoE−/− mice fed a high-fat diet is promising, as there is substantial evidence to suggest Treg numbers and function are impaired during atherosclerosis development." (PMID 33516262, 2021).